RNU6-567P (RNA, U6 small nuclear 567, pseudogene)
Gene: Small nuclear RNA gene on chromosome 18 (60,018,625 to 60,018,731, forward strand). Ensembl gene ENSG00000252555.
Homologues: Orthologues: chimpanzee U6 (98% identical), macaque U6 (86% identical), rat LOC120095357 (79% identical), mouse Gm23545 (74% identical). Paralogues in human: RNU6-1159P (83% identical), RNU6-115P (82% identical), RNU6-1209P (81% identical), RNU6-797P (81% identical), RNU6-1287P (80% identical), RNU6-1025P (79% identical), RNU6-1094P (79% identical), RNU6-1181P (79% identical), RNU6-16P (79% identical), RNU6-414P (79% identical), RNU6-776P (79% identical), RNU6-1091P (79% identical), and 1285 more.